CCL5 (C-C motif chemokine ligand 5)
Diseases named in the same sentence as CCL5 in open-access papers (continued):
Sharing a sentence is not in itself a finding about the gene and the disease.
breast cancer (continued). "Furthermore, quantum dots were utilized to image and detect the chemokine (C-C motif) ligand 5 (CCL5) and collagen IV in luminal B (HER2-negative) breast cancer, with the aim of calculating the CCL5/collagen IV ratio to determine its prognostic value." (PMID 38730959, 2024). "CCL5 has been reported to trigger invasion by increasing the release of matrix metalloproteinases 2 and 9 in prostate cancer and cancer cell motility and invasion by being secreted by mesenchymal stem cells in the TME in breast cancer." (PMID 39329983, 2024). "In this study, we showed that TI-NK cells act as major contributors to early CCL5/IFN-ɣ production along anti-HER2 antibody treatment in primary breast cancer patients, disclosing the role of the IFN-ɣ/CCL5/CXCL9 axis in the effectiveness of neoadjuvant treatment with anti-HER2 antibodies." (PMID 38167224, 2024). "Additionally, it revealed a cooperative effect between IFN-γ and TNF-α in inducing the production of CCL5 and CXCL9 from breast cancer cells." (PMID 38167224, 2024). "Secretion of free fatty acids as well as cytokines and growth factors, including Monocyte chemoattractant protein 1 (MCP-1), C-C motif chemokine ligand 5 (CCL5), and Insulin-like growth factor 1 (IGF-1), also promote breast cancer cell invasion and proliferation." (PMID 38473978, 2024). "Previous literature data reported that CCL5, but not the other three cytokines, is highly secreted by breast cancer cells compared to normal cells." (PMID 36765778, 2023). "Furthermore, CD163+macrophages were found to be located around adipocytes in breast cancer tissues, and their recruitment and polarization were mediated by the upregulated expression of CCL2 and CCL5 in the TAME." (PMID 37454080, 2023). "Thus, the reciprocal expression pattern of CCL5 and specifically CCR1 suggests a predominant chemokine/receptor interaction between CCL5-producing ASCs and CCR1-expressing basal breast cancer cells in the 3D co-spheroids." (PMID 37444610, 2023). "Serum CCL5 levels in BCa patients correlated with lymph node metastasis and analysis of Tregs, which promote tumor metastasis, showed CCR5+/CD4+ and Treg/CCR5+ cell ratios were significantly increased in the lymph nodes of the breast cancer metastasis group." (PMID 37759462, 2023). "Bioinformatics analysis of in silico publicly available TNBC data identified BCL3 and BCL2 as well as the following anti-tumour immune response biomarkers as significantly altered in TNBC compared to other breast cancer subtypes: GZMA, PRF1, CXCL1, CCL2, CCL4, and CCL5." (PMID 38022682, 2023). "Since the effects of recombinant human CCL5 (CCL5 rh) on breast cancer progression have been reported, as the final step of this study, we aimed to prove whether the action of DHEA occurs through CCL5." (PMID 36765778, 2023). "C-C motif chemokine ligand 5 (CCL5), also known as RANTES (Regulated on Activation, Normal T cell Expressed and Secreted), has been described as a metastasis-promoting chemokine that is expressed upon the crosstalk between breast cancer and stromal cells." (PMID 37444610, 2023). "The mean follow-up time was 30.07 (5-52 months), and the results showed that breast cancer patients negative for CCL5 had better DFS (P =0.027) and BCSS (P =0.013)." (PMID 36033472, 2022). "In addition to CCL5 levels, even CCR5 receptor expression is higher in breast cancer tissues compared to normal tissues." (PMID 36430633, 2022). "Subsequently, in order to assess the effect of magnifying CCL5 on breast cancer metastatic ability, transwell assays with or without coating by matrigel were preformed to acquire functional significance of CCL5 on MDA-MB-231 cells invasion and migration." (PMID 36090993, 2022).
breast cancer (continued). "The difference is that the targets of PD1/PDL1 are TILs, and tumor progression can be promoted by inactivation of TILs; however, our study confirmed that CCL5/CCR5 affects breast cancer progression and the survival of breast cancer patients by affecting the Treg/CCR5+ cell ratio." (PMID 36033472, 2022). "CCR5 siRNA did not reduce the metastatic phenotype of MDA-MB-231 cells in the absence of additional MDSC, endothelial cells produce CCL5, and augmented breast cancer metastasis in another study." (PMID 33485378, 2021). "Indeed, we detected a significantly increased tumor CCL5 expression and F4/80+ macrophage infiltration in the primary tumors when stably RKIP knockdown mouse 4T1 breast cancer cells were transplanted orthotopically into mice." (PMID 34465801, 2021). "Breast cancer-derived exosomes were shown to promote a myofibroblastic phenotype in adipose tissue-derived mesenchymal stem cells, resulting in increased expression of the tumor-promoting factors, TGF-β, VEGF, stromal cell-derived factor 1 (SDF-1), and CCL5." (PMID 34283044, 2021). "Meanwhile, combination of the STAT3 inhibitor and anti-PD-1 antibody synergistically improved T cells activation, CCL5 and IFN-γ releasing in the TME as compared toanti-PD-1 alone, and decreased tumor-infiltrating Tregs, therefore inhibiting the breast cancer progression and metastasis." (PMID 33957948, 2021). "The major transcriptional effects of DMHCA were linked to transrepression of a network of LXR-responsive genes, including PTGS2, S100A9, SPP1, CD14, CCL5 and ANXA1, which are overexpressed in MDSC and in a significant proportion of breast cancers, where they denote poor survival." (PMID 33780491, 2021). "In contrast, CCL5 was secreted in equivalent amounts by all breast cancer cells, irrespective of the receptor expression status or malignant potential." (PMID 33912188, 2021). "TAMs are recruited to mammary tumors through induction of a variety of cytokines and chemokines including C-C Motif Chemokine Ligand 2 (CCL2), CCL3, CCL5, Colony Stimulating Facotor-1 (CSF-1/M-CSF), and Granulocyte-Macrophage Colony-Stimulating Factor (GM-CSF or CSF2)." (PMID 34298673, 2021). "Actually, the risk of recurrence was significantly higher in patients with breast carcinomas positive for CCL5 and CCR3 but negative for CCR1 and CCR5." (PMID 33671956, 2021). "More importantly, the expression of CCL5 and/or its receptors have so far not been well-examined in human breast carcinoma tissues." (PMID 33671956, 2021). "During the last decade, CCL5 has been shown to be an inductor of resistance to taxane, CDDP, tamoxifen and Src inhibitors in models of prostate cancer, ovarian cancer and breast cancer, respectively." (PMID 31990955, 2020). "On the contrary, recent studies using CCL5 knockout mice showed that the total absence of host CCL5 exhibits increased antitumor immunity in breast cancer models, proposing a unique procancer role of host CCL520,21." (PMID 32218434, 2020). "Breast cancer-derived T-EVs nurture a myofibroblastic phenotype in adipose tissue-derived MSCs (Ad-MSCs), accompanied by enhanced VEGF, TGF-β, stromal cell-derived factor 1 (SDF-1), and C-C motif chemokine ligand 5 (CCL5) expression." (PMID 33081785, 2020). "Our results imply that ZA treatment might reduce the ability of breast cancer cells to enhance the expansion and migration of Tregs by reducing their production of CCL2 and CCL5." (PMID 30808421, 2019). "Compared to normal controls, MIAT was down-regulated in luminal B breast cancer tumor tissues which were inconsistent with our results, while S100A7, CCL5 and WT1-AS were up-regulated in luminal B breast cancer tumor tissues which were consistent with our results." (PMID 31795964, 2019). "CCL5 expression correlates at some extent with markers of stemness (cancer and normal stem cells) and with EMT markers in the analysis including all the intrinsic molecular breast cancer subtypes." (PMID 31921621, 2019).
breast cancer (continued). "Among the factors secreted by macrophages, CCL18 was reported to have strong effects on breast cancer progression whereas macrophage-secreted IL-1β, TNF-α, and CCL5 were previously suppressed by IL-32θ; thus, mRNA expression levels of these factors were measured." (PMID 31126309, 2019). "The inflammatory chemokine CCL5 and/or its receptor, CCR5, are expressed in various human cancers, including breast cancer, prostate cancer, ovarian and cervical cancer, gastric and colon cancer, melanoma, multiple myeloma, Hodgkin’s lymphoma, and T-acute lymphoblastic leukemia." (PMID 30154786, 2018). "SNAIL1 activates expression of CCL2, CCL5, IL-6, TNFα, and IL-8 in head and neck cancer cells and overexpression of SNAIL1 in 4T1 cells increased infiltration of M2-like macrophages and promoted metastasis in a breast cancer orthotopic model." (PMID 29593211, 2018). "Thus, our results open up avenues to the possibility of targeting CCL5 and Ezrin as a strategy to inhibit the effect of MAF on metastasis, predominantly in BRCA1 defective breast cancers." (PMID 30224826, 2018). "CCR4, whose ligands are CCL2, CCL3, CCL5, CCL17 and CCL22, is crucial for immune cell homeostasis but is also involved in hematologic malignancies, such as adult T-cell leukemia and Hodgkin’s lymphomas, and some solid tumors, including breast cancer." (PMID 30591657, 2018). "Additionally, it was found that the release of osteopontin (OPN) by tumour cells induced the production of CCL5 by MSCs, which in turn promoted CCR5 mediated breast cancer cell metastasis." (PMID 28148268, 2017). "In earlier studies we have shown that CCL5 activation of CCR5 induces the proliferation and survival of breast cancer cells in a mechanistic target of rapamycin (mTOR)-dependent manner and that this is in part due to CCR5-mediated increases in glycolytic metabolism." (PMID 29216863, 2017). "In earlier studies, we showed that CCL5 engagement with its cognate receptor, CCR5, results in the up-regulation of mRNA translation of pro-survival factors leading to enhanced proliferation in MCF-7 breast cancer cells." (PMID 29216863, 2017). "In addition, the osteocytes within the bone microenvironment were found to promote cancer invasion and growth by secretion of CCL5, MMP and extracellular ATP and adenosine in prostate cancer and breast cancer." (PMID 29197379, 2017). "It has been shown that CCL5 induces the invasion of basal breast cancer cells (i.e. MDA-MB-231 cells) but not of luminal breast cancer cells (i.e. MCF-7 cells)." (PMID 27027351, 2016). "In earlier studies, we showed that CCL5 enhances proliferation and survival of MCF-7 breast cancer cells in an mTOR-dependent manner and we provided evidence that, for T cells, CCL5 activation of CCR5 results in increased glycolysis and enhanced ATP production." (PMID 27335323, 2016). "The role of CCL5 in breast cancer progression and metastasis has been established: this includes upregulation of MMP secretion, pro-tumor effects by generating MDSC in the bone marrow, and a reduction in metastasis when low levels of CCL5 are expressed." (PMID 27169366, 2016). "Notably, CCL5 engagement with its cognate receptor, CCR5, results in the rapid upregulation of mRNA translation of pro-survival factors in MCF-7 breast cancer cells." (PMID 27335323, 2016). "Next, we evaluated whether CCL5 and IGF-1 could be detected in peritumoral adipose tissue of women with breast cancer." (PMID 27027351, 2016). "This causal negative role of RKIP on CCL5 expression is clinically relevant because a statistically significant negative correlation of RKIP and CCL5 expression was also observed in breast cancer clinical samples." (PMID 26375811, 2015). "Concurring with a decrease in CCL5 mRNA expression in RKIP expressing breast cancer cells, we also observed a decrease in CCL5 protein expression in RKIP-expressing 4T1 tumor by immunohistochemical (IHC) staining with CCL5 specific Ab." (PMID 26375811, 2015).
breast cancer (continued). "Since CCL5 stimulates invasion of breast cancer cells, it is possible that RKIP inhibits cancer cells invasion by decreasing CCL5 expression and silencing of RKIP increases invasion because of the increased CCL5 expression." (PMID 26375811, 2015). "Here, we identified the impact of TNF-α and IL-1β on the inflammatory phenotype of CAFs and MSCs by determining the expression of inflammatory chemokines that are well-characterized as pro-tumorigenic in breast cancer: CCL2 (MCP-1), CXCL8 (IL-8) and CCL5 (RANTES)." (PMID 25928089, 2015). "In addition, a modified version of CCL5, Met-CCL5 with an antagonistic activity on CCR1 and CCR5, showed antitumor effect reducing infiltrating inflammatory cells in a breast cancer model." (PMID 26062132, 2015). "Discrepancy between CCL5 gene expression and survival in HER2+ breast cancer may also arise from confounding clinical factors in the survival analysis that are independent of either therapeutic resistance or metastatic site." (PMID 26173622, 2015). "Hypoxia induces a strong increase of both CCL5 and CCR5 expressions by breast cancer cells." (PMID 24523569, 2014). "Although three factors, namely CCL5, IL6, and MMP13 are up-regulated during the interaction, in vitro and in vivo studies indicate that CCL5 is the key contributor to the metastatic characteristics of breast cancer." (PMID 25072326, 2014). "A microarray analysis on 2,254 human breast cancer specimens found increased expression of CCL5 and its receptor CCR5, but not CCR3, in the basal and HER-2 genetic subtypes." (PMID 24523569, 2014). "UBE2C expression was associated with that of the selected metastasis-related genes VEGF, CXCL-4, CCL5, NEDD9 and RHoC, in MCF-7 cells, so UBE2C may be involved in breast cancer metastasis." (PMID 24699941, 2014). "Carriers of CCL5-rs2107538 CT/TT genotypes or CCL5-rs3817655 AT/AA genotypes were 40% less likely to be diagnosed with ER negative breast cancer compared to women who had CC or TT genotype, respectively." (PMID 23991131, 2013). "CCL5 affects the prognosis and metastasis of breast cancer through C–C motif chemokine receptor 5 (CCR5)/Treg signaling pathway, which may serve as a potential therapeutic target for immunotherapy against breast cancer." (PMID 40016717, 2025). "In a mouse model of breast cancer, treatment with Met‐CCL5 (a CCR5 antagonist) for 5 continuous weeks resulted in significant reductions in tumor volume and weight compared with those of control tumors, indicating the activity of Met‐CCL5 against established tumors." (PMID 40452814, 2025). "Furthermore, in breast cancer, CCL2 and CCL5 expression is restricted not only to tumor cells but also to cells of the tumor microenvironment, including fibroblasts, endothelial cells, mesenchymal stem cells, smooth muscle cells and immune cells such as tumor-associated macrophages and T cells." (PMID 38928033, 2024). "For instance, it was demonstrated that CCL2/monocyte chemoattractant protein-1, CCL5, IL-1β, IL-6, tumor necrosis factor α, vascular endothelial growth factor, and leptin released by CAAs in the TME promote the proliferation, and dissemination of breast cancer cells." (PMID 36980280, 2023). "Notably, the cytokines CCL5/RANTES, CXCL10/IP-10, and ICAM/CD54 increase tumour cell motility and invasion, with CXCL10/IP-10 and ICAM/CD54 also enhancing a metastatic phenotype in breast cancer tumour cells." (PMID 36949770, 2023). "However, tumor-derived CCL5 does not act as the significant contributor to mammary carcinoma growth, and hematopoietic-derived CCL5 promotes tumor progression via the generation of MDSCs and maintenance of its immunosuppressive properties." (PMID 35327361, 2022). "However, poly(I:C) alone did not induce IFNβ, IL-8, Ccl5, or Cxcl10 mRNAs in a panel of six human breast carcinoma cell lines." (PMID 35737804, 2022).
breast cancer (continued). "Also, CCL5 was found to be increased, and chemokine/chemokine receptor signature was enriched after CDK4/6 inhibitor treatment in a phase II study in HR+/HER2− breast cancer patients and in a mouse model of mammary tumors, which are in agreement with our findings." (PMID 37181790, 2022). "CCL5 is under a phase 1 clinical trial for autoimmune diabetes, while ST14, found in the minimal gene signature analysis, is patented-recorded and whose proposed functions include an important role in breast cancer invasion and metastasis according to the TTD database." (PMID 34316711, 2021). "From these findings, we speculated that CCL5 might promote breast cancer progression via CCR3 but not CCR1 or CCR5." (PMID 33671956, 2021). "We further examined whether CCL5 and CCR1, 3 and 5 served as prognostic factors in breast cancers." (PMID 33671956, 2021). "However, the expression on CCL5 and its receptors have so far not been well-examined in human breast carcinoma tissues." (PMID 33671956, 2021). "Furthermore, the risk of recurrence was significantly higher in the patients with breast carcinomas positive for CCL5 and CCR3 but negative for CCR1 and CCR5, as compared with other patients." (PMID 33671956, 2021). "Interestingly, recent studies using CCL5 knockout mice showed that the absence of host CCL5 enhances antitumor immunity of neutrophils and T cells in breast cancer models." (PMID 32218434, 2020). "CCL5 and/or CCR5 overexpression has been found in many tumors, including acute lymphocytic leukemia, Hodgkin lymphoma, multiple myeloma, breast cancer, colorectal carcinoma, esophageal cancer, gastric adenocarcinoma, head and neck cancer, melanoma, pancreatic cancer, and prostate cancer." (PMID 32630699, 2020). "CAAs secrete more chemokine (C–C motif) ligand 2 (CCL2), chemokine (C–C motif) ligand 5 (CCL5), interleukin-1β (IL-1β), interleukin-6 (IL-6), tumor necrosis factor-alpha (TNF-α), vascular endothelial growth factor (VEGF), leptin, etc., which can promote the invasion and metastasis of breast cancer." (PMID 31500658, 2019). "Likewise, the inflammatory chemokine CCL5, interacting primarily with G protein-coupled receptor CCR5, is highly expressed in several cancers, including breast cancer, and has been shown to play an important pro-oncogenic role via immune cell recruitment, tumor growth, chemotaxis, and apoptosis." (PMID 31191817, 2019). "Development of BCSCs by MSC-mediated enhanced release of chemokines including CCL5/RANTES and subsequent activation of cancer cell dissemination and metastasis can also be triggered via MSC-stimulated expression of the EMT markers Snail, Twist, Vimentin, and N-cadherin in breast cancer cells." (PMID 31557960, 2019). "However, we and others showed that tumor-derived CCL5 expression did not significantly promote mammary carcinoma growth, but the hematopoietic CCL5 played the major role in BC progression by regulating myeloid cells or macrophages in different subtype of BC." (PMID 31921621, 2019). "Indeed, no induction of CCL5 gene expression by adipocyte factors has been detected in breast cancer cells." (PMID 27027351, 2016). "Nevertheless, CCL5/CCR5 expression levels are different among the different genetic subtypes of breast cancer and may represent a negative prognostic factor." (PMID 27027351, 2016). "To conclude, based on several studies done in patients, animal model systems, and in vitro systems, the CCL5/CCR5 axis seems to have a crucial role in cancer progression and may represent an important breast cancer therapeutic target with minimal adverse impact." (PMID 24523569, 2014). "As previous study has reported that blocking of STAT3 in breast cancer cells induced an antitumor immune response involving CD4+ T cells, which may ameliorate TME via secretion of cytokines, such as TNF-α, IFN-γ, IL-6, and IL-5, as well as chemokines CCL5 and CXCL10." (PMID 33957948, 2021).